SMYD3 (SET and MYND domain containing 3)
Diseases named in the same sentence as SMYD3 in open-access papers (continued):
Sharing a sentence is not in itself a finding about the gene and the disease.
tumor (continued). "Importantly, in this study we used EM127, a site-specific SMYD3 covalent inhibitor, in several experimental models that recapitulate tumor complexity and, as such, are more relevant to clinical practice." (PMID 40588481, 2025). "Since upregulated SMYD3 shapes the immunosuppressive microenvironment in ccRCC through the SREBP1‐CD47 axis, pharmacological inhibition of SMYD3 may have a synergistic effect with PD‐1 inhibitors to achieve increased tumor therapeutic efficacy." (PMID 40548645, 2025). "We demonstrated that elevated Smyd3-Shcbp1 signaling could reprogram the tumor immunosuppressive microenvironment (TIME) and promote immune therapy resistance upon αPD1 treatment." (PMID 40157910, 2025). "Moreover, SMYD3 knockdown inhibits tumor metastasis and reduces ascites volume in both peritoneal seeding and patient-derived xenograft (PDX) models." (PMID 39482529, 2024). "After 12 days, the tumor volume in HCT116-SMYD3-KO-xenografted mice was significantly lower compared to HCT116-xenografted mice, in line with previous studies showing that SMYD3 deficiency inhibits tumor development." (PMID 38812026, 2024). "Notably, areas of partial tumor regression showed high SMYD3 expression in the viable part of the residual tumor." (PMID 38812026, 2024). "SMYD3 depletion inhibits cell proliferation, colony formation, and xenograft tumor growth." (PMID 39482529, 2024). "S3, A and B), suggesting a role for SMYD3 in tumor growth in vivo." (PMID 37976356, 2023). "Moreover, IHC confirmed that SMYD3-depleted SGC-7901 tumor masses manifested significantly weaker Ki-67 staining than the tumor masses derived from the control cells." (PMID 37386026, 2023). "Furthermore, patients with higher SMYD3 expression had larger tumor sizes and a more advanced pT stage." (PMID 37386026, 2023). "Ectopic expression of SMYD3WT restored the growth rate, whereas SMYD3F183A expression caused a similarly slow rate of tumor growth as cells without SMYD3." (PMID 37976356, 2023). "In addition, we investigated the role of SMYD3 in tumor development and progression in vivo by subcutaneously implanting LM3 cells that had been engineered to stably express SMYD3 shRNA or control scrambled shRNA into athymic BALB/c mice." (PMID 36575438, 2022). "The results revealed that tumor growth was substantially decreased in response to SMYD3 knockdown." (PMID 36575438, 2022). "Notably, analyses of tumor biopsy lysates showed that SMYD3 expression is higher in TKO-mutant mice treated with CP compared with naïve tumor samples, suggesting that increased SMYD3 expression correlates with prolonged exposure to CP." (PMID 35819319, 2022). "Especially in BC, high SMYD3 expression promotes tumor cell proliferation." (PMID 34335697, 2021). "Specifically, we selected a tumor subset that is HR-proficient, and therefore addicted to high levels of SMYD3, as a candidate for this new therapeutic strategy based on the impairment of HR repair response with a specific SMYD3i to make the tumor sensitive to PARPi." (PMID 34503239, 2021). "Similar to SMYD3, other factors that are directly involved in cell cycle regulation, such as cyclins and CDKs, are frequently deregulated in GI tumors and these alterations are correlated with less favorable tumor phenotypes and poor prognosis." (PMID 34503239, 2021). "Furthermore, a large amount of evidence indicates critical roles for SMYD3 in the proliferation, invasion, and migration of different tumor cells." (PMID 34301921, 2021). "In vivo mouse models demonstrated that SMYD3 knockdown reduced tumor growth." (PMID 33637115, 2021). "To investigate if SMYD3 may play a role in development, we first analyzed Smyd3 expression levels in non-tumor derived cells." (PMID 34069776, 2021). "In the cytoplasm, SMYD3 has been found to affect key factors involved in oncogenic pathways by interacting with and methylating non-histone proteins, which suggests a role as a modulator of signaling cascades promoting tumor progression." (PMID 34503239, 2021).
tumor (continued). "Thus, SMYD3 depletion significantly suppressed tumor growth and oncogenic potential of BC cells both in vitro and in vivo." (PMID 32007952, 2020). "SMYD3 mRNA expression was up-regulated in HCC tumor tissues compared to other tissues (P = 0.008)." (PMID 32071406, 2020). "Overall, these data suggest that the combination of different SMYD3-mediated regulatory loops may affect distinct facets of proliferation in different tumor cells." (PMID 31935919, 2020). "SMYD3 mRNA expression was higher in stage-B tumor tissues compared to that in stage-A tissues." (PMID 32071406, 2020). "These evidences depict SMYD3 as a modulator of the transcriptional response and of key signaling pathways, orchestrating multiple oncogenic inputs and ultimately, promoting transcriptional reprogramming and tumor transformation." (PMID 31935919, 2020). "Remarkably, SMYD3 knockdown inhibits tumor sphere growth and the number of sphere-initiating cells." (PMID 31935919, 2020). "We next asked how SMYD3 depletion inhibited tumor growth of BC cell lines." (PMID 32007952, 2020). "Moreover, SMYD3 knockdown inhibited tumor metastasis and reduced ascites volume in xenograft models." (PMID 31935919, 2020). "SMYD3 was successfully knocked-down in tumor of SMYD3 knockdown group (p=0.04)." (PMID 31417652, 2019). "This indicates that SMYD3 might adopt an integrated model that combines signaling and epigenetic pathways to contribute to tumor cell proliferation and growth." (PMID 31737645, 2019). "Therefore, our data reveal a new mechanism for ANKHD1 in promoting tumor progression, serving as a “reader” protein coordinating with SMYD3 to promote target gene expression." (PMID 30646949, 2019). "However, the exact role of SMYD3 in promoting tumor invasion and metastasis in HCC remains to be elucidated." (PMID 30646949, 2019). "Therefore, SMYD3 putatively regulated A2780 cells tumor- related gene expression by lysine methylation of certain important signal molecule in cytoplasm." (PMID 31417652, 2019). "It now remains to be seen whether chemical inhibition of SMYD2 or SMYD3 in vivo would affect an already existing tumor and hence be a valuable drug target." (PMID 29856759, 2018). "We found that the expression of SMYD3 was suppressed in the subcutaneous tumor." (PMID 29029425, 2017). "We also detected the expression of SMYD3 in tumor section by IHC." (PMID 29029425, 2017). "These functional terms are presumed to be significantly mediated by SMYD3 through its DEGs and could also be applied to explore the molecular roles of SMYD3 in ESCC tumor initiation and growth." (PMID 28781952, 2017). "In accordance with previous findings in other tumor models, we hypothesized that the oncogenic properties of SMYD3 could depend on its histone methyltransferase activity." (PMID 25980436, 2015). "SMYD3 protein levels did not correlate with primary site, stage, tumor size (T), lymph node stage (N), metastatic stage (M), age or gender; however, a significant association was found with both smoking history and tumor grade." (PMID 39762343, 2025). "Furthermore, treatment with the SMYD3 chemical inhibitor BCI-121 exerted anti-tumor effects." (PMID 37237385, 2023). "However, how RNF113A is activated and regulated remains unclear, and we sought to determine whether the regulation of RNF113A activity by SMYD3 methylation may be a potential mechanism of tumor resistance to alkylation damage." (PMID 35819319, 2022). "Therefore, targeting this pathway may be applicable in all SCLC subtypes, and it is likely that the depicted pathway can participate in other tumor contexts where SMYD3 overexpression is observed." (PMID 35819319, 2022). "Moreover, CD97 and SMYD3 promote tumor progression by regulating MMP2." (PMID 34007838, 2021). "Furthermore, higher SMYD3 expression levels correlated with higher tumor grade and worse survival." (PMID 33637115, 2021).
tumor (continued). "In order to determine whether Src association with the HMGA2 and SMYD3 promoters is maintained in the patients’ tumors in vivo, we performed ChIP on samples derived from formalin-fixed paraffin embedded (FFPE) tumor blocks utilizing the newly developed PAT-ChIP method." (PMID 26695438, 2016). "In addition to its usefulness as a biomarker for clinically aggressive disease, SMYD3 overexpression might also constitute an attractive therapeutic target in PCa because its tumor-promoting properties are mostly due to its histone methyltransferase activity." (PMID 25980436, 2015). "Interestingly, since SMYD3 is able to promote either the active H3K4me3 or the repressive H4K20me3 marks, it has been suggested that it might act either by repressing tumor suppressor genes or inducing oncogenes' expression." (PMID 25980436, 2015). "Although these studies provided preliminary clues pointing to a major role for SMYD3 in CSC biology, further investigation is needed to clarify its involvement in tumor formation and metastatic dissemination." (PMID 40588481, 2025). "Smyd3 ASOs reinvigorated CD8+ T‐cells and promoted anti‐tumor neutrophils, as well as a Treg and M2 macrophage phenotype in vivo." (PMID 40548645, 2025). "Given that SMYD3 regulates CD47 expression, we next explored the effects of CD47 on tumor growth and the infiltration of Th2 cells." (PMID 40548645, 2025). "The data revealed that the expression of Smyd3 and Esr1 at the mRNA level was increased in MTV, MTP12, and tumor tissues compared with age-matched Brca1-WT controls." (PMID 40157910, 2025). "In the tumor‐bearing animals, ZYZ384 was found to inhibit the growth of implanted HepG2 tumors in nude mice correlating with the inhibition of SMYD3." (PMID 39286779, 2024). "Knockdown of SMYD3 and expression of SMYD3WT or SMYD3F183A was confirmed in tumor samples using immunoblotting." (PMID 37976356, 2023). "As a result of reduced SMYD3 expression, SGC-7901 cells grew at a significantly decreased rate, and the weights of the harvested tumor masses were markedly reduced." (PMID 37386026, 2023). "To study the implication of SMYD3 in SCLC, we have extended our observation to patient-derived tumor xenografts and mouse models." (PMID 35819319, 2022). "Tumor burden in TKO and TKO;Smyd3-mutant mice was evaluated using microcomputed tomography (μCT), and when tumors reached a volume of approximately 40 mm3, animals were treated with CP." (PMID 35819319, 2022). "The SMYD3-overexpressing and S1PR1-overexpressing groups showed significantly increased tumor growth compared to the control group." (PMID 34301921, 2021). "SMYD3 levels in HCC were also analyzed in TCGA dataset, confirming that its upregulation is correlated with the development of new tumor foci, HCC progression to high-grade disease and poorer overall survival." (PMID 34503239, 2021). "In this study, SMYD3, STAT3, and pSTAT3 expression levels were significantly higher in GC tissues than non-tumor tissues and positively correlated with each other." (PMID 33637115, 2021). "SMYD3 is a methyltransferase that methylates H3K4 and H4K5 and overexpression has been observed in a variety of tumor types." (PMID 29985390, 2018). "The protein levels of Smyd3 and H3K4me3 were also elevated in both MTP12 and tumor tissues." (PMID 40157910, 2025). "The data revealed that disruption of either SMYD3 or SHCBP1 in MDA-MB-231 cells did not affect cell growth in vitro but significantly inhibited tumor growth in both 231 and HCC1937 mice models with reversed the splenomegaly phenotype." (PMID 40157910, 2025). "Furthermore, Smyd3 protein levels in MTP12 mammary glands and tumor tissues of Brca1MKO mice were elevated compared to their controls, as shown by IHC staining." (PMID 40157910, 2025). "Importantly, Smyd3 depletion through antisense oligonucleotides increased CD8 + T-cell influx and sensitized an HPV-negative mouse flank tumor model to anti-PD-1 therapy." (PMID 39762343, 2025).
tumor (continued). "Because elevated Smyd3-Shcbp1 signaling increases the PD1 and CD8 double-positive cell population, we next explored single and double treatment with Tra and αPD1 in tumor-bearing FVB mice, which have an intact immune system, with implantation of HP5712 cells." (PMID 40157910, 2025). "In summary, this study demonstrates that SMYD3 depletion significantly impairs the proliferative capacity, cell cycling and the invasive potential of HPV-negative HNSCC cells, while it also hinders tumor growth in vivo." (PMID 39762343, 2025). "We achieved this by constructing a tumor cell line with stable SMYD3 knockdown, without altering the expression levels of SMYD3 in the immune cells." (PMID 40548645, 2025). "Because Smyd3 was identified form premalignant MTP12 cell, we also tested whether pregnancy could shape the TME and benefit the tumor growth with implantation of HP cells at P15 and 7 days after birth." (PMID 40157910, 2025). "In addition, we identified mutations in epigenetic regulation genes, such as KMT2D, KMT2E, SMYD3, ASH1L, KMT2C, and KMD4B, in the tumor clones." (PMID 38010945, 2024). "Nascent tumorigenic cells have been found to activate the SMYD3–H3K4m3 pathway to upregulate CSDE1 expression and stabilize phosphatase, TCPTP, promoting STAT1 dephosphorylation and weakening the immunogenic phenotype of tumor-repopulating cells." (PMID 37237385, 2023). "Despite the high expression levels of SMYD3 in other tumor types, including PCa, the prosurvival and prometastatic pathways dependent on SMYD3 signaling have not been clearly defined in these cells." (PMID 37976356, 2023). "In summary, these data support our overall hypothesis that SMYD3 cooperates with the NuRD (MTA1/MTA2) complex to inhibit expression of a series of tumor suppressor genes, leading to tumor progression." (PMID 36575438, 2022). "In this study, we conducted RNA-seq analysis on 5 pairs of HCC and adjacent noncancerous tissues and found that SMYD3 was highly expressed in tumor tissue." (PMID 36575438, 2022). "Thus, both SMYD3 and RNF113A seem to be key proteins for tumor sensitivity and acquired resistance to various chemotherapeutic drugs." (PMID 35819319, 2022). "SMYD3 interaction with AMPK and mTOR may allow tumor cells to overcome the metabolic stress conditions to which they are typically exposed and stabilize their adaptive metabolic reprogramming." (PMID 35495117, 2022). "The results from TCGA database also indicated increased expression levels of SMYD3 in tumor tissues compared to noncancerous tissues, and its expression tended to be positively correlated with disease stage progression." (PMID 36575438, 2022). "Furthermore, knockdown of SMYD3 suppressed ESCC cell proliferation, migration, and invasion in vitro and inhibited local tumor invasion in vivo." (PMID 33637115, 2021). "SMYD3, as a histone H3K4 methyltransferase, has received considerable attention in the last few years due to its critical roles in multiple malignant processes, especially in tumor invasion and metastasis." (PMID 30646949, 2019). "Of note, mice lacking SMYD3 are viable and often their phenotype appears only upon a given challenge (i.e. tumor induction), which suggests a role of this protein in the fine-tuning of specific tissue/cell responses that might alter susceptibility to disease." (PMID 38148333, 2024). "﻿ Additionally, we observed a negative correlation between SMYD3 mRNA expression and methylation levels on particular probes, such as cg06985779 and cg15962031, with a concomitant reduction in DNA methylation levels of SMYD3 in tumor samples." (PMID 37237385, 2023). "Finally, we performed xenograft tumor growth studies using H1092 SCLC cells either depleted for SMYD3 via CRISPR/Cas9 or treated with SMYD3i, with and without CP treatment." (PMID 35819319, 2022).
tumor (continued). "However, this study tested the in vitro effect of SMYD3 expression and/or activity impairment without taking into account the roles of tumor heterogeneity and the microenvironment." (PMID 31935919, 2020). "However, in a mouse model, SMYD3 knockdown was able to reduce tumor formation by LNCaP cells, but PC3 cells were not tested." (PMID 25980436, 2015). "To determine whether SMYD3 drives tumor immune evasion via CD47 upregulation and subsequent activation of SREBP1 expression, we overexpressed SREBP1 in stable SMYD3‐knockdown 786‐O and TK10 cells to investigate whether the effects of SMYD3 knockdown could be eliminated upon SREBP1 overexpression." (PMID 40548645, 2025). "Furthermore, a different study indicated that SMYD3 knockdown induced transcriptional upregulation of CD8 + T-cell attracting chemokines and APM components in HNSCC cells, also showing SMYD3 might mediate tumor progression and immune escape." (PMID 37237385, 2023). "Necroscopic evaluation revealed the complete absence of tumor masses in 60% of EM127-treated mice vs 0% of mice treated with the vehicle, suggesting a role for SMYD3 inhibition in preventing CRC metastatic spreading." (PMID 40588481, 2025). "In addition, since SMYD3 has been implicated in CHK2 phosphorylation, which is a marker of resistance and has previously been detected in resistant RC tissues, we analyzed its levels in AOM/DSS-induced mice tumor samples treated with irinotecan in combination or not with EM127." (PMID 38812026, 2024).
infection (4 papers, 2017 to 2021). The state of being infected such as from the introduction of a foreign agent such as serum, vaccine, antigenic substance or organism. "Theileria infection induces the reversible expression of the histone methyltransferase SMYD3, which also has H3K4 methylation activity." (PMID 33557100, 2021). "Replication of EBOV was significantly decreased in target cells treated with SMYD3 specific siRNAs compared to those treated with negative control siRNA after infection of trVLPs." (PMID 31516086, 2019). "Growth curves at a 12-day time point following infection of Hep3B cells also showed little difference in growth between controls and SMYD3 targeting sgRNAs (data not shown)." (PMID 29856759, 2018).
gastrointestinal tumors (3 papers, 2021 to 2025). "Interestingly, a significant proportion of HR-proficient gastrointestinal tumors expressing high levels of SMYD3 from the PanCanAtlas dataset seem to be eligible for this innovative strategy." (PMID 34503239, 2021).
prostate (3 papers, 2015 to 2025). "In conclusion, our data provide further evidence to sustain an oncogenic role for SMYD3 in prostate carcinogenesis." (PMID 25980436, 2015).
kidney disorder (1 paper, 2022). A disease involving the kidney. "We identified two loci, RNLS (encoding renalase) and SMYD3 (SET and MYND domain containing 3), that are associated with kidney disorders in the REGARDS study but did not replicate in the GenHAT study." (PMID 36250097, 2022).
SMYD3 also shares sentences with these, for which no sentence is quoted: acute myeloid leukemia (2 papers); Alzheimer disease (1); bipolar disorder (1); COVID-19 (1); cutaneous T-cell lymphoma (1); endothelial dysfunction (1); gout (1); gynecological cancers (1); heart failure (1); Hepatic steatosis (1); hepatitis B virus (1); insomnia (1); Intellectual disability (1); invasive ductal carcinoma (1); invasive lobular carcinomas (1); leiomyosarcoma (1); lipid metabolism disorders (1); myelodysplastic syndrome (1); myeloma (1); neurological disorders (1); peripheral T-cell lymphoma (1); rectal cancer (1); renal Wilms' tumor (1); squamous cell carcinoma (1); tongue squamous cell carcinoma (1).